SMARCD3 (SWI/SNF related BAF chromatin remodeling complex subunit D3)
Diseases named in the same sentence as SMARCD3 in open-access papers (continued):
Sharing a sentence is not in itself a finding about the gene and the disease.
colon cancer (1 paper, 2020). "Correlation analyses using SMARCD3 expression data and clinical features of colon cancer patients from TCGA indicated that SMARCD3 expression is associated with lymphatic invasion, OS and copy number etc.." (PMID 33125346, 2020). "Gene expression data analyses based on colon cancer data from TCGA indicated that SMARCD3 is under expressed in cancer tissues comparing with normal control." (PMID 33125346, 2020). "Interestingly, SMARCD3 expression in primary colon tumor is higher than in polyps." (PMID 33125346, 2020).
complication (1 paper, 2018). Any disease or disorder that occurs during the course of, or because of, another disease, treatment, or procedure. "TRIB3 rs2295490, ATF6 rs12086247, and SMARCD3 rs58125572 genetic variants are associated with specific treatment protocols and with the incidence of diabetic vascular complications." (PMID 30618737, 2018).
gastric tumor (1 paper, 2025). "Furthermore, WNT3A-induced WNT pathway activation synergizes with SMARCD3 to enhance EMT progression, underscoring the complex interplay of signaling cascades in gastric tumor biology." (PMID 41228321, 2025).
melanoma (1 paper, 2022). A malignant, usually aggressive tumor composed of atypical, neoplastic melanocytes. "The genes encoding these subunits are mutated at low frequency in melanoma, with SMARCD3 being slightly more frequently altered then the SMARCD1 and SMARCD2 genes." (PMID 35323214, 2022). "Furthermore, the demonstrated roles of SMARCD3 in glycolytic metabolism and lipogenesis could have implications for melanocyte development and melanoma proliferation." (PMID 35323214, 2022).
pancreatitis (1 paper, 2023). Inflammation of the pancreas. "While SMARCD3 was rarely expressed in benign inflamed tissue (pancreatitis), the frequency of nuclear SMARCD3+ epithelial cells rose in PanIN and, to a greater degree, in PDAC in a human tissue microarray." (PMID 36653361, 2023).
Sepsis (1 paper, 2025). Sepsis is defined as life-threatening organ dysfunction caused by a dysregulated host response to infection. "Additionally, chromatin remodeling influences the epigenetics of immune cells in sepsis, suggesting an indirect link between SMARCD3 and ARDS development." (PMID 41221285, 2025).
T-cell acute lymphoblastic leukemia (1 paper, 2023). Acute lymphoblastic leukemia of T-cell origin. "A microarray model system identified that the SMARCD3 gene is upregulated in T-cell acute lymphoblastic leukemia." (PMID 37480069, 2023).
tumor (14 papers, 2016 to 2025). "First, we analyzed the relationship between SMARCD3 and tumor mutational burden in 33 cancers." (PMID 38862250, 2024). "Single-cell RNA sequencing (scRNA-seq) reveals a migrating tumor cell population with elevated SMARCD3 expression in males, a finding that is less pronounced in females." (PMID 41510281, 2025). "Mechanistically, high SMARCD3 expression drives tumor aggressiveness by promoting the Epithelial–Mesenchymal Transition (EMT) phenotype." (PMID 41228321, 2025). "The findings of the study indicated that the levels of SMARCD3 expression in tumor cell lines from three different types of cancer were lower than those in normal cell lines." (PMID 38862250, 2024). "In 4 of these cancers (CHOL, KIRP, LIHC and THCA), SMARCD3 expression was lower in normal tissues than in tumor tissues." (PMID 38862250, 2024). "In this study, we used KIRC, LUAD, and STAD tumor and normal cell lines to assess and validate the expression levels and variations of SMARCD3." (PMID 38862250, 2024). "Further, tamoxifen-mediated Smarcd3 deletion led to a ~3-fold drop in total free fatty acid content in EpCAM+ Smarcd3f/f-KPF-R26-CreERT2 tumor cells in vivo, as determined by gas chromatography–mass spectrometry (GC–MS)." (PMID 36653361, 2023). "IHC analysis revealed a positive correlation between SMARCD3 and p-Src (Y416), both of which were highly increased in metastatic tumours compared with the paired primary tumours." (PMID 36849558, 2023). "Collectively, our in vitro and in vivo loss-of-function and gain-of-function studies together with the patient data analysis suggest that SMARCD3 acts as the main driver in tumour metastatic dissemination in the evolution of MB." (PMID 36849558, 2023). "Despite advanced tumor stage at enrollment, Smarcd3 deletion reduced total tumor cell and EpCAM+ tumor cell number by 1.5 fold." (PMID 36653361, 2023). "Mice bearing orthotopic xenograft tumours with SMARCD3 KO or OE exhibited moderate survival differences compared with the controls." (PMID 36849558, 2023). "Although a significant difference between the two groups was not obtained, there was a trend in shorter survival times in mice bearing SMARCD3 + MYCS62D-induced tumours compared with MYCS62D-induced tumours." (PMID 36849558, 2023). "Consistently, overexpression (OE) of SMARCD3 in D425 cells increased cell migration, spinal metastasis and the percentage of tumour-bearing mice with CTCs." (PMID 36849558, 2023). "Functionally, we use diverse stage-specific conditional genetic models to show that Smarcd3 deletion specifically impacts established tumor growth, synergizing with chemotherapy to improve survival in tumors post-establishment." (PMID 36653361, 2023). "Similar to SMARCD3 tumour expression, we observed higher levels of p-Src in the tumour margin than in the centre." (PMID 36849558, 2023). "ATF5 was significantly expressed on Mono/Macro and pDC subgroups in tumor cells, whereas C1orf53 was predominantly expressed on Mono/Macro subgroup and SMARCD3 was predominantly expressed on Mast subgroup." (PMID 37859813, 2023). "Here, we showed that SMARCD3 was mainly expressed in fibroblasts and was associated with EMT and tumor metastasis." (PMID 33125346, 2020). "This shows that SMARCD3 affects substance metabolism, especially lipid metabolism, and may thereby affect tumor progression." (PMID 38862250, 2024). "Our study revealed that SMARCD3 may be an important gene and a potential tumor target and provides a direction for further research." (PMID 38862250, 2024). "Given that SMARCD3 affects DNA damage repair, cellular aging may also be one of the mechanisms by which SMARCD3 affects tumor development." (PMID 38862250, 2024). "In the other 13 cancers, SMARCD3 was expressed at lower levels in tumor tissues." (PMID 38862250, 2024). "SMARCD3 may also promote or inhibit the development and occurrence of tumors by impacting immune cell activities in the tumor microenvironment." (PMID 38862250, 2024).
tumor (continued). "Moreover, SMARCD3 was highly expressed in the tumour margin compared with the tumour centre, which suggests that MB cells with high SMARCD3 levels tend to spread from the primary tumour site." (PMID 36849558, 2023). "Smarcd3 deletion led to a 2-fold reduction in total tumor mass, tumor area, and tumor cell number in tamoxifen-treated mice even though escaper SMARCD3 re-expression could be detected in some tumors." (PMID 36653361, 2023). "To better understand how Smarcd3 contributes to the establishment and sustained propagation of cancer cells through the course of tumor progression in vivo, we used a diverse set of autochthonous genetic models to delete Smarcd3 in a temporally restricted manner." (PMID 36653361, 2023). "To determine whether increased SMARCD3 levels contribute to MB development, we used virus-induced spontaneous tumour formation in postnatal C57BL/6J mice." (PMID 36849558, 2023). "We classified the five tumours into higher or lower levels of SMARCD3 mRNA expression." (PMID 36849558, 2023). "Smarcd3 deletion led to a greater significant loss (3-fold) in EpCAM+ tumor cells, and a 3.5-fold reduction in EpCAM+MSI2+ tumor stem cells in secondary transplants, suggesting that Smarcd3 deletion reduces the self-renewal capability of established tumor cells." (PMID 36653361, 2023). "By contrast, MYCS62D-induced tumours promoted by SMARCD3 OE led to spinal metastases." (PMID 36849558, 2023). "Furthermore, SMARCD3 deletion reduced p-Src levels in MED8A and D458 cells and in xenograft tumours derived from these cells, suggesting that Src activation is induced by increased SMARCD3 expression." (PMID 36849558, 2023). "We asked whether SMARCD3 levels are increased in metastatic tumours and in turn whether SFKs are activated." (PMID 36849558, 2023). "Moreover, SMARCD3 OE D425-derived GFP+ mice had enhanced tumour dissemination in the spinal cord and the local brain compared with WT D425-derived GFP+ mice." (PMID 36849558, 2023). "The regulation of prostaglandin synthesis by SMARCD3 could also impact inflammation in the tumor microenvironment." (PMID 36653361, 2023). "As a subunit of a chromatin-modifying complex, SMARCD3 may control tumor cell function by regulating SWI/SNF binding and the epigenetic landscape." (PMID 36653361, 2023). "However, in most cancers, SMARCD3 is expressed at low levels in tumor tissues." (PMID 38862250, 2024). "However, in most cancers, SMARCD3 expression is lower in tumor tissues." (PMID 38862250, 2024). "Moreover, patients with higher SMARCD3 levels had a higher frequency of tumour metastasis." (PMID 36849558, 2023). "Consistent with this, proximity ligation and co-immunoprecipitation showed FOXA1 interacting with both SMARCD3 and SMARCA4 in KPf/fC tumor cells; this interaction was enriched in primary KPf/fC stem cells." (PMID 36653361, 2023). "Collectively, these results indicate that MB hijacks SMARCD3–Reelin–DAB1-mediated cell migration, a neurodevelopmental programme in the cerebellum, to promote tumour metastatic dissemination." (PMID 36849558, 2023). "Supporting a role for SMARCD3 and FOXA1 in cancer stem cells, SMARCD3/FOXA1 interactions were enriched within the nuclei of primary CD133+ mouse tumor cells and Foxa1 knockdown severely reduced sphere formation in KPf/fC cells." (PMID 36653361, 2023). "To assess the impact of Smarcd3 deletion directly in the autochthonous KPF model, we tracked tumor emergence by palpation and enrolled CRE+ and CRE− tumor-bearing KPF mice into treatment with tamoxifen followed by tumor analysis three weeks later." (PMID 36653361, 2023). "Further, shRNA-mediated knockdown of Smarcd3 in MSI2+ KPf/fC cells almost completely blocked flank tumor growth in NOD-SCID mice in vivo, reducing growth rate by over 4-fold, and total tumor cell and MSI2+ tumor stem cell counts by 2.5 and 3.5-fold." (PMID 36653361, 2023).
tumor (continued). "This indicates that SMARCD3 overexpression is sufficient to drive tumor growth even in the absence of this critical oncogene, supporting a pro-tumorigenic function for Smarcd3 in PDAC." (PMID 36653361, 2023). "Furthermore, GFP fluorescence analyses showed no obvious differences in tumour size of MYCS62D-induced tumours with or without SMARCD3 OE." (PMID 36849558, 2023). "Notably, OE of constitutively active MYCS62D alone and MYCS62D + SMARCD3 induced tumour formation; however, SMARCD3 OE alone did not." (PMID 36849558, 2023). "Thus, SMARCD3 may not have a robust impact on early tumor initiation, although its restricted ductal expression in the normal mouse pancreas (as opposed to the ubiquitous expression of SMARCA4) suggests a potential role in ductal fate." (PMID 36653361, 2023).
cancer (11 papers, 2020 to 2025). A tumor composed of atypical neoplastic, often pleomorphic cells that invade other tissues. "Furthermore, in the colorectal cancer microenvironment, SMARCD3 expression is enriched in cancer-associated fibroblasts (CAFs) and promotes metastasis through positive feedback loops involving WNT5A, TGF-β, and MAPK signaling." (PMID 41228321, 2025). "The effects of SMARCD3 on chromatin remodeling, DNA synthesis and DNA damage repair are likely to be among the mechanisms underlying this process, as this gene affects the course and prognosis of malignant tumors." (PMID 38862250, 2024). "Both cholesterol and fatty acid metabolism are enriched in cancer stem cells and have been associated with stem cell signaling and therapy resistance in many cancers, indicating that SMARCD3 may regulate stem cell-enriched metabolic pathways." (PMID 36653361, 2023). "Subsequently, an evaluation was conducted to ascertain the prognostic relevance of SMARCD3 for various kinds of cancer." (PMID 38862250, 2024). "Combining gene expression and gene activity analysis, we found that in most cancers with low SMARCD3 expression and activity, such as BLCA, LUAD, KIRC, PAAD and STAD." (PMID 38862250, 2024). "The TMB and MSI of cancer are negatively correlated with the expression of SMARCD3; that is, low expression and activity of SMARCD3 are associated with increased TMB and MSI." (PMID 38862250, 2024). "There seems to be a special mechanism by which the expression and gene activity of SMARCD3 are inhibited in cancer." (PMID 38862250, 2024). "Compared to patients with high SMARCD3 expression, those with reduced SMARCD3 expression had a better prognosis for the remaining 4 cancers." (PMID 38862250, 2024). "Next, we evaluated the relationships of SMARCD3 with the ImmuneScore and StromalScore in different cancers." (PMID 38862250, 2024). "In our study, we found heterogeneity in the expression and role of SMARCD3 in various cancers, but its effects on cancer are mostly unfavorable, and it is a risk factor for various cancers." (PMID 38862250, 2024). "We conducted this research to systematically assess the function of SMARCD3 across cancers and provide specific directions for subsequent research on SMARCD3." (PMID 38862250, 2024). "Further, Smarcd3 knockdown drove down the expression of core enzymes involved in the metabolism of lipid families with known functions in cancer: cholesterol, prostaglandins, and fatty acids." (PMID 36653361, 2023). "Mechanistically, SMARCD3 acts with FOXA1 to control lipid and fatty acid metabolism, programs associated with therapy resistance and poor prognosis in cancer." (PMID 36653361, 2023). "Consistent with this, SMARCD3 was required for the propagation of patient-derived xenografts in vivo, providing strong evidence that Smarcd3 is required for advanced cancer growth." (PMID 36653361, 2023). "In this pathway, the role of reelin is pivotal, as reelin was found to be directly regulated by a key epigenetic modulator, SMARCD3, to launch a cascade of factors that trigger cancer cell metastasis." (PMID 37728789, 2023). "The authors of that study identified that overexpression of SMARCD3 in medulloblastoma activates reelin–DAB1–Src signaling-mediated cancer cell migration, which eventually results in metastatic dissemination." (PMID 37728789, 2023). "Therefore, we conducted this research to investigate the potential involvement of SMARCD3 across cancers and to offer recommendations for future studies." (PMID 38862250, 2024). "We believe that SMARCD3 has more research value among these four cancers." (PMID 38862250, 2024). "Our study systematically evaluated the function of SMARCD3 across cancers." (PMID 38862250, 2024). "First, we analyzed SMARCD3 expression and patient prognosis in 33 cancers." (PMID 38862250, 2024). "Next, we created KM curves to evaluate the predictive significance of SMARCD3 across cancers." (PMID 38862250, 2024).
cancer (continued). "GSEA revealed that SMARCD3 may exert effects on lipid metabolism and immune cell activity as potential mechanism in cancer." (PMID 38862250, 2024). "We examined the expression features and prognostic significance of SMARCD3 across cancers and found that SMARCD3 may be an important gene affecting COAD, HNSC, KIRC, LUAD, STAD and UCEC." (PMID 38862250, 2024). "Therefore, the purpose of this research was to reveal the function of SMARCD3 across cancers and to offer a novel avenue for investigating its mode of action in particular cancer types." (PMID 38862250, 2024). "The mechanisms by which SMARCD3 may sense metabolic status could provide insight into the role of SWI/SNF in regulating metabolic plasticity in cancer." (PMID 36653361, 2023). "In contrast to our findings that Smarcd3 is a potential cancer dependency, the cancer dependency DepMap database shows that SMARCD3 is an enrichment in cancer cell lines, further suggesting that SMARCD3 function may be context-dependent." (PMID 36653361, 2023). "Because loss-of-function alterations in SMARCD3 have not been identified in cancer, it is unlikely that its deletion significantly drives tumorigenesis in human disease." (PMID 36653361, 2023). "Collectively, our results position SMARCD3 as an oncogenic SWI/SNF subunit that could drive important metabolic functions in aggressive cancer cells and serve as an effective target for new therapies." (PMID 36653361, 2023). "For instance, SMARCD3 has an activation effect in 6 over 32 cancer types (approximately 19%)." (PMID 33125346, 2020). "This may be a mechanism by which SMARCD3 affects cancer development." (PMID 38862250, 2024). "SMARCD3 cooperates with FOXA1 to control lipid and fatty acid metabolism, resulting in therapy resistance and poor prognosis in cancer." (PMID 40454484, 2025). "The ESTIMATEScore was positively correlated with SMARCD3 expression in COAD, PRAD, and READ, indicating that immune cells and stromal cells are highly infiltrated in these three cancers." (PMID 38862250, 2024). "The expression of SMARCD3 differed between LUAD cancer tissues and normal tissues, with low expression in cancer tissues." (PMID 38862250, 2024). "We also noted that the activity of the SMARCD3 gene in LGG, PCPG, and GBM was greater than that in other cancers." (PMID 38862250, 2024). "We found that SMARCD3 expression was negatively correlated with the TMB and MSI in most cancers, especially in KIRC, LUAD, STAD and UCEC." (PMID 38862250, 2024). "SMARCD3 is a subunit of SWI/SNF, a nucleosome remodeling complex with core functions in development and cancer." (PMID 36653361, 2023). "We asked whether a positive correlation between SMARCD3 and DAB1 exists in other human cancers or healthy organs." (PMID 36849558, 2023). "SMARCD3, BRD9, JDP2, were also reported to be a oncogene role in some cancer." (PMID 36506326, 2022). "However, to date, SMARCD3 has not been well studied, and its involvement in cancer has not been fully explained." (PMID 38862250, 2024). "Similarly, the fact that SMARCD3 is elevated from PanIN to PDAC suggests that it may be required to support ductal fate later in disease progression, and serve as an important enabler of SMARCA4 function in cancer." (PMID 36653361, 2023).
bacterial infection (1 paper, 2022). "SMARCD3 and EBI3, two genes over-expressed in bacterial infection, are associated with tuberculosis infection and bacterial burden." (PMID 36543117, 2022).
immune diseases (1 paper, 2024). "In addition, genes related to immune diseases (e.g., BID, SMARCD3, ATP6V1E1, NFKB2), energy metabolism (e.g., HAO1, NDUFA7, CERS4, MTHFD1), and other factors were also screened." (PMID 38750582, 2024).
neurological disorders (1 paper, 2023). "This process is hijacked in MB metastasis, thereby implicating an important role of SMARCD3 in neurodevelopment and neurological disorders." (PMID 36849558, 2023).
prostate (1 paper, 2022). "Similarly to SMARCD1, we found that numerous downstream targets of SMARCD2 (e.g., PTGR1, TRMP8, PGC) and SMARCD3 (e.g., EGF, PIK3AP1, HSD3B1) were AR-driven genes that are involved in prostate tumorigenesis, progression and metastasis." (PMID 36611918, 2022).